IL6 (interleukin 6)
Diseases named in the same sentence as IL6 in open-access papers (continued):
Sharing a sentence is not in itself a finding about the gene and the disease.
colorectal cancer (continued). "When evaluated for combined expression, IL-6 and IL-12p70 in patients with colorectal cancer closely related to lymph node metastasis and TNM staging." (PMID 36226059, 2022). "The IL-6-mediated STAT3 signaling pathway is the main target for the treatment of colorectal cancer and IBD." (PMID 35645824, 2022). "In colorectal cancer, IL-6 promoted cell proliferation and drug resistance through its downstream signaling molecules, such as STAT3, representing potential molecular targets for cancer therapy." (PMID 36091805, 2022). "Our results show that the IL-6 levels of patients with neutral colorectal cancer in late clinical staging were higher (P <0.05) and the TNF-α levels of patients with low division were higher (P<0.05)." (PMID 36226059, 2022). "IL-6 is significantly highly expressed in the stroma of some malignancies, such as in prostate and colorectal cancers where it can influence tumor growth and differentiation." (PMID 36531035, 2022). "On the other hand, knockdown of human miR-375 upregulates NF-κB and pro-inflammatory factors, such as tumor necrosis factor-α, IL-1β, IL-6 and IL-8, in the colorectal cancer cell line Caco-2." (PMID 35052815, 2022). "For example, serum TNF‐α, IL‐1β, IL‐6, and IL‐8 are positively associated with elevated HADS score in colorectal cancer patients." (PMID 34697903, 2022). "The serum levels of IL-6 in patients with colorectal cancer (CRC) are correlated with the malignant tumor grade, and high IL-6 levels (≥10 pg/mL) are an independent indicator of poor prognosis." (PMID 36010693, 2022). "One study provided evidence that interleukin 6 (IL6) secreted by MSCs promoted increased expression of CD133 in CSCs of murine colorectal cancer via the JAK-STAT signaling pathway." (PMID 35629138, 2022). "We started with the evaluation of levels of IL-6, TNF-α and IL-12P7, and observed that IL-6 levels are associated with lymph node metastasis and the TNM staging in patients with colorectal cancer (t = 6.705, -4.224, P <0.05)." (PMID 36226059, 2022). "Several clinical or experimental studies pointed out a relationship between interleukin-6 (IL-6) and inflammation in patients with colorectal cancer." (PMID 36361758, 2022). "In colorectal cancer cells, IL-6 potentiates the Fra-1 activity by inducing the HDAC6-mediated Fra-1 deacetylation and accumulation, resulting in the gain of stem-like features, partially dependent on the Fra-1-mediated transactivation of the NANOG promoter." (PMID 35326630, 2022). "In contrast, in other tumours, high expression levels of IL-6 have been correlated with impaired survival in triple-negative breast cancer, ovarian cancer and colorectal cancer and have been detected in the serum of metastatic prostate cancer patients." (PMID 35022523, 2022). "For instance, CAF-derived IL-6 supports cancer cells’ EMT and metastasis by IL-6/STAT signaling in colorectal cancer, gastric cancer, and pancreatic cancer." (PMID 35327514, 2022). "Downregulation of IFN-γ and TNF-α, along with the upregulation of IL-6 and IL-8, has been observed in colorectal cancer." (PMID 36035429, 2022). "In patients with IBD or colorectal cancer, the levels of circulating and colonic IL-6 were increased, which were also found in the DSS- or AOM/DSS-treated mice." (PMID 35865942, 2022). "Consistently, recent research showed that GZMA promote the colorectal cancer progression by inducing IL-6 production through NF-κB and activating pSTAT3 in colorectal cancer." (PMID 35534879, 2022). "In colorectal cancer, IL-6 activates autophagy by the interaction of JAK2 and Becn1 because JAK2 acts as a protein kinase that phosphorylates Becn1 at Y333 to promote autophagy initiation." (PMID 36311768, 2022). "In a colorectal cancer model, IL6 and angiopoietin 1 secreted by MSCs provoked cancer cells to produce endothelin 1, resulting in the promotion of cancer angiogenesis." (PMID 35629138, 2022).
colorectal cancer (continued). "Excessive secretion of IL-6 promotes the reproduction of epithelial cells and even induces colorectal cancer." (PMID 35681301, 2022). "Reduced levels of pro-inflammatory C-reactive protein, IL6, antibiotic use and length of hospital stay after surgery, and morbidity in colorectal cancer patients in the post-operative period." (PMID 35711771, 2022). "A study detected the IL-6 level of patients in the ERAS group and the control group after colorectal cancer surgery, and it was disclosed that the IL-6 level in the ERAS group after 1, 3, and 5 d of surgery was lower than that in the control group." (PMID 35844438, 2022). "Fra-1 contributes to both autocrine and paracrine mechanisms of EMT and tumor angiogenesis, by inducing multiple cytokines, including TGF-beta in breast and colorectal cancer cells, and IL-6 and VEGF in the TAMs recruited to tumor microenvironment." (PMID 35326630, 2022). "Colonic myofibroblasts are CD90+ innate immune cells secreting IL-6, which favors stemness and enhances adaptive inflammatory response to assist tumor growth in colorectal cancer." (PMID 36550571, 2022). "The interleukin-6 (IL-6) has been reported to be a crucial tumor-promoting cytokine, and its expression is significantly increased in colorectal carcinoma." (PMID 36448791, 2022). "The increase of proinflammatory factors, including IL-1β, TNF-α, and IL-6, will aggravate intestinal inflammation and promote the occurrence of colorectal cancer." (PMID 34594475, 2021). "In colorectal cancer, TAMs activate the IL-6/STAT3/miR-204-5p pathway by secreting IL-6, which supports cancer progression, increases the resistance of colorectal cancer to chemotherapeutic drugs and reduces drug-induced apoptosis." (PMID 33722297, 2021). "Based on GSE136682 data, we found that IL-1β and IL-6 were increased in the intestinal tumor of mice after gavage administration by feces from colorectal cancer patients compared to their counterparts of mice fed by feces from healthy people." (PMID 34863291, 2021). "Mihaela group developed an impedimetric aptasensor for the label-free selective detection of interleukin-6 (IL-6) for colorectal cancer screening." (PMID 34960590, 2021). "TNF- α increased levels of pro-inflammatory cytokines, such as IL-6 and IL-8 in vitro on HT-29 colorectal cancer cells." (PMID 34631734, 2021). "TLR7 binding to exosomal miR-21 was also reported to mediate liver macrophage polarization toward an interleukin-6 (IL-6)-secreting pro-inflammatory phenotype, thus providing a favorable environment for colorectal cancer liver metastasis." (PMID 34595207, 2021). "Our previous study presented that IL-6 concentration significantly decreased 12 days after colorectal cancer resection, as compared to values obtained 3 days after surgery." (PMID 34441316, 2021). "Some studies using quantitative PCR (qPCR) have shown that the mRNA levels of interleukin-8 (IL-8) and IL-6 in colorectal cancer (CRC) cells that were penetrated by F.n were significantly increased 43,44." (PMID 34093809, 2021). "The study of the relationship between interleukin-6 (IL-6) and tumor markers in breast and colorectal cancers is an example of such a combination, as well as one of the research hotspots." (PMID 34439874, 2021). "Data in the literature correlated elevated serum levels of IL-6 in colorectal cancer (CRC) patients with advanced tumors and poor prognosis." (PMID 34829995, 2021). "For instance, IL-1β, and IL-6 are highly expressed in colorectal cancer and infiltrating IL-1β receptor/IL-6 producing cells are increased in the stroma, which stimulates tumor cell growth." (PMID 33406733, 2021). "In our work, IL-1β and IL-6 were increased in the intestinal tumors of mice after being fed by feces from colorectal cancer patients compared to counterparts fed by feces from healthy people." (PMID 34863291, 2021).
colorectal cancer (continued). "Taken together, serum IL-6 was up-regulated in colorectal cancer patients and in ApcMin/+ mice, and IL-6 was increased in both colorectal cancer tissues and cells." (PMID 34863141, 2021). "Further study found that MetS-genes were associated with the effectiveness of targeted chemotherapy for CRC and the MetS core gene IL6 would promote the malignancy of colorectal cancer through mTOR-S6K signaling." (PMID 33582655, 2021). "Mechanistically, IL-6/JAK2 signaling-mediated phosphorylation of BECN1 at Y333 by contributes to chemotherapy resistance in colorectal cancer, and the pharmacological inhibition of autophagy leads to reestablishment of chemotherapy sensitivity." (PMID 34131122, 2021). "On the one hand, Kitamura et al49 demonstrated that downregulation of HLA class II expression induced by interleukin-6/STAT3 signaling activation hampered dendritic cells activating effector T cells in colorectal cancer." (PMID 34362829, 2021). "IL-6 is an inflammatory cytokine and plays important roles in microenviroment of colorectal cancers." (PMID 34046355, 2021). "Inflammatory mediators IL-1β, TNF-α, and IL-6 are increased at the early onset of colorectal cancer, and inhibiting the production of these cytokines can be an effective strategy to prevent colon cancer development." (PMID 34684488, 2021). "Several studies have shown that inhibition of IL-6 enhances the therapeutic efficacy of α-PD-L1 therapy in melanoma, colorectal cancer, pancreatic cancer and hepatocellular carcinoma 45-48." (PMID 34093869, 2021). "Here, we show that cancer-associated fibroblast (CAF)-activated stromal signaling, interleukin-6/8-JAK2, induces BRD4 phosphorylation at tyrosine 97/98 in colorectal cancer, resulting in BRD4 stabilization due to interaction with the deubiquitinase UCHL3." (PMID 34290255, 2021). "It has recently been demonstrated that interleukin-6 induces a nucleus-to-cytosol shift of hMSH3, leading to DNA mismatch repair defects in colorectal cancer cells." (PMID 33923292, 2021). "The levels of IL-6 are dramatically increased in serum and tumor samples of humans and mice with colorectal cancer, and high IL-6 levels in colorectal cancers are found to correlate with poor prognosis 54-55." (PMID 33767595, 2021). "Our in vitro/vivo results are consistent with those of previous studies, showing that IL-6 overexpression leads to significant chemotherapy resistance in colorectal cancer." (PMID 34131122, 2021). "Clinical data also showed that serum IL-6 in colorectal cancer patients were significantly higher than the healthy group." (PMID 34863141, 2021). "In the present study, we demonstrated that IL-6 activates autophagy in colorectal cancer, leading to the interaction between JAK2 and BECN1." (PMID 34131122, 2021). "The initiation of autophagy induced by the IL-6/JAK2/BECN1 signaling pathway appears to be a regulatory mechanism for chemotherapy resistance in colorectal cancer." (PMID 34131122, 2021). "Data in the literature already showed the role of IL-6 in different steps of tumor development, such as in modeling the immune responses in cancers and in colorectal cancer." (PMID 34829995, 2021). "Here the authors show that IL-6 activates autophagy in colorectal cancer through the interaction between JAK2 and autophagy regulator, BECN1, which leads to chemotherapeutic resistance." (PMID 34131122, 2021). "Increased IL-6 expression has been related to advanced stages of disease and decreased survival in colorectal cancer patients, it activates JAKs with a subsequent activation of STAT3 through phosphorylation." (PMID 32422984, 2020). "Inhibition of IL-6 enhanced the efficacy of anti-PD-L1 antibodies in colorectal cancer providing a novel strategy to overcome anti-PD-L1 resistance." (PMID 33096896, 2020). "Thereafter, BK has shown to increase IL-6 production via B2R in colorectal cancer cell, and the B2R-antagonist icatibant was able to inhibit the BK-induced IL-6 release." (PMID 32849666, 2020).
colorectal cancer (continued). "IL-6 is one of the abundantly expressed cytokines in the colorectal cancer microenvironment through gp130 activation on tumor cells with subsequent signaling through Janus kinases (JAKs) and signal transducers and activation of transcription 3 (STAT3)." (PMID 32422984, 2020). "Simultaneously, several studies indicated that several inflammation indicators including NLR, PLR, LMR, interleukin-6 and platelet correlated with the prognosis of colorectal cancer." (PMID 33141155, 2020). "Dysregulation of the IL-6/STAT3 signaling pathway has an important role in the development of colorectal cancer." (PMID 30832202, 2019). "For instance, the tyrosine kinase Bcr-Abl stimulates STAT3 (Ser727) phosphorylation via JAK/MEK signaling, whereas the Bcr-Abl kinase inhibitor ponatinib suppresses IL-6-stimulated STAT3 phosphorylation in human colorectal cancer (CRC) cells." (PMID 31655606, 2019). "The multi-targeted TKI ponatinib was shown to inhibit STAT3 phosphorylation driven by EGFR and interleukin 6, leading to suppression of colorectal cancer cell growth and migration." (PMID 31422383, 2019). "Patients who suffer from colorectal cancer exhibit high serum levels of inflammatory mediators such as IL-1β, IL-6, TNF-α and PGE227,28." (PMID 31511625, 2019). "Some studies have reported that tumor-infiltrating immune cells such as M1 macrophages secrete high levels of IL-6 as an anti-tumor mediator, and that the increased accumulation of IL-6 is related to better prognosis in colorectal cancers." (PMID 30927911, 2019). "In another study, it was reported that conditioned media derived-MSCs culture includes IL-6 able to induce expression of Oct4 and Sox2 as pluripotent markers in colorectal cancer stem cells (CSCs)." (PMID 31009502, 2019). "In relation to colon cancer, it was shown that IL-6/STAT3-driven EMT in a colorectal cancer model requires miR-34a suppression." (PMID 31557902, 2019). "It has been reported that IL-6 promotes the proliferation and invasion of colorectal cancer cells through Ras/MAPK and PI3K/AKT signaling." (PMID 29348540, 2018). "Only 48 articles were included in the results of this review, as only English, clinical studies concerning the clinical use of IL-6 in gastric cancer, bile duct cancer, pancreatic cancer and colorectal cancer were included." (PMID 30038723, 2018). "Western blotting analysis revealed that CC-MSC-CM resulted in increased phosphorylation of JAK2, STAT3, and AKT in colorectal cancer cells; all three were activated by stimulation with IL-6." (PMID 29348540, 2018). "Finding a parallel increase in IL-6 serum levels with increasing stage of colorectal cancer and increasing metastatic regional lymph nodes in our study supports that opinion." (PMID 30154846, 2018). "In the present study, we detected higher levels of IL-6 expression in the CC-MSCs than in the control, which suggested that IL-6 probably plays a significant part in the invasion and metastasis of colorectal cancer." (PMID 29348540, 2018). "Taken together, these results demonstrated that IL-6, secreted from CC-MSCs, contributed to colorectal cancer progression." (PMID 29348540, 2018). "IL-6 was the most highly expressed cytokine in the human colorectal cancer-derived mesenchymal stem cells conditioned medium, and promoted the progression of colorectal cancer cells through IL-6/JAK2/STAT3 signaling, which activated PI3K/AKT signaling." (PMID 30175384, 2018). "More than 200.000 articles has been published regarding gastric-, pancreatic-, bile duct- and colorectal cancer, however it is interesting that only 48 articles assessed the clinical use of IL-6 as a biomarker." (PMID 30038723, 2018).
colorectal cancer (continued). "In brief, our results indicate that CC-MSCs enhance colorectal cancer progression through the activation of IL-6/JAK2/STAT3 signaling." (PMID 29348540, 2018). "To determine the role of IL-6 in the tumorigenesis of colorectal cancer, we established an APCMin/+ mice mouse model and determined the cytokine profile in tissue interstitial fluid (TIF) by performing an AAM-CYT-G3 cytokine antibody array." (PMID 29707119, 2018). "B2R activation-induced IL-6 production has also been described in synovial fibroblast and colorectal cancer cells, suggesting that BK signaling mediates pro-inflammatory responses." (PMID 30619185, 2018). "IL-6 has been shown to inhibit the tumor suppressing immune cells in colorectal cancer cells by down-regulating the activity of cytotoxic T-lymphocytes through suppression of the maturation of dendrite cells." (PMID 30038723, 2018). "Since the colorectal cancer studies involved a large number of patients showing different results, the results regarding colorectal cancer and IL-6 seems inconclusive." (PMID 30038723, 2018). "TNFα is destructive to tumor blood vessels and induces cell death by necrosis at high concentrations while elevated levels of IL-6 are also present in numerous tumors such as colorectal cancer, gastric carcinoma, and Hodgkin lymphoma." (PMID 30622433, 2018). "The aim of this study to evaluate mutual relation between IL-6, CRP and MMP-9 serum levels in patients with CRC and their association with staging and clinical-pathological features of colorectal cancer." (PMID 30154846, 2018). "A recent study showed that IL-6, and particularly IL-11, play a potent pro-tumorigenic role in colorectal cancer models in mice." (PMID 29652830, 2018). "Taken together, these data showed that the effect of the CC-MSCs on colorectal cancer progression was dependent on IL-6 and STAT3 activation." (PMID 29348540, 2018). "IL-6 is a cytokine; it accompanies inflammation, and is involved in the progression of cancers, including colorectal cancer." (PMID 29348540, 2018). "The results regarding the prognostic use of IL-6 in colorectal cancer were unfortunately too equivocal to allow firm conclusions." (PMID 30038723, 2018). "In our TCGA gene dataset for colorectal cancer, we found that IL-6, EMT, and inflammation signaling were decreased in the metformin-predicted group." (PMID 30308035, 2018). "Other studies have provided evidence that cytokines pertaining to the IL-6 cytokine family play an important role in colorectal cancer formation." (PMID 29652830, 2018). "This systematic review found 48 publications investigating IL-6 as a cancer biomarker in 5316 patients with gastric, bile duct, gallbladder, pancreatic and colorectal cancer." (PMID 30038723, 2018). "They found that the pooled HR was 1.76 (95% CI 1.42–2.19), indicating that high serum IL-6 in colorectal cancer patients is a predictor of short OS." (PMID 30038723, 2018). "Sixteen studies assessed the use of serum IL-6 as a prognostic biomarker in patients with colorectal cancer with contradicting results." (PMID 30038723, 2018). "The cell studies described for the four types of GI cancer (gastric cancer, biliary duct cancer, pancreatic cancer and colorectal cancer) provide a solid base for documenting the impact of IL-6 in the development, growth and invasion of these cancers." (PMID 30038723, 2018). "The results of the meta-analysis do, however, show IL-6 to be significant as a prognostic biomarker for OS in colorectal cancer." (PMID 30038723, 2018). "The aim of this study was to evaluate interleukin-6 (IL-6), C-reactive protein (CRP), matrix metalloproteinase-9 (MMP-9), serum levels in patients with colorectal cancer (CRC), and their association with the stage of CRC." (PMID 30154846, 2018). "Previous studies demonstrated a poorer overall survival (OS) and progression-free survival (PFS) of colorectal cancer patients with high IL-6 serum levels compared to patients with low IL-6 serum levels." (PMID 28927416, 2017).